ZNF98 (zinc finger protein 98)
Description:
May be involved in transcriptional regulation.
Synonyms: ZNF739; F7175
Tractability: PROTAC: ubiquitination databases record sites on it.
Gene: Protein-coding gene on chromosome 19 (22,391,019 to 22,532,485, reverse strand). Ensembl gene ENSG00000197360.
Subcellular location: Nucleus
Gene Ontology:
Molecular function: DNA-binding transcription factor activity, RNA polymerase II-specific; RNA polymerase II cis-regulatory region sequence-specific DNA binding; DNA-binding transcription repressor activity, RNA polymerase II-specific
Biological process: regulation of DNA-templated transcription; negative regulation of transcription by RNA polymerase II; regulation of transcription by RNA polymerase II
Cellular component: nucleus
Genetic constraint (gnomAD): Loss-of-function variants: 9 observed, 10.56 expected, observed/expected ratio (o/e) 0.85, 90% interval 0.51 to 1.48. The synonymous counts are far from expectation, so gnomAD's model fits this gene poorly and the ratio says little. Missense variants: 374 observed, 557.83 expected, observed/expected ratio (o/e) 0.67, 90% interval 0.62 to 0.73. Synonymous variants: 110 observed, 181.73 expected, observed/expected ratio (o/e) 0.61, 90% interval 0.52 to 0.71.
Homologues: Orthologues: chimpanzee ZNF92 (65% identical). Paralogues in human: ZNF92 (70% identical), ZNF430 (68% identical), ZNF730 (68% identical), ZNF431 (66% identical), ZNF737 (66% identical), ZNF675 (65% identical), ZNF257 (65% identical), ZNF66 (64% identical), ZNF680 (64% identical), ZNF723 (63% identical), ZNF273 (62% identical), ZNF626 (61% identical), and 6 more.
Diseases named in the same sentence as ZNF98 in open-access papers:
ZNF98 is named in the same sentence as 1 disease in open-access papers, as found by Europe PMC text mining. Sharing a sentence is not in itself a finding about the gene and the disease. The quoted sentences say what the papers report.
tumour (1 paper, 2024). "The AC2 cluster was characterised by an overexpression of genes like MMP26, ZNF98 and SP100 associated with tumour promotion." (PMID 39167619, 2024).